EMC9 (ER membrane protein complex subunit 9)
Description:
Part of the endoplasmic reticulum membrane protein complex (EMC) that enables the energy-independent insertion into endoplasmic reticulum membranes of newly synthesized membrane proteins. Preferentially accommodates proteins with transmembrane domains that are weakly hydrophobic or contain destabilizing features such as charged and aromatic residues. Involved in the cotranslational insertion of multi-pass membrane proteins in which stop-transfer membrane-anchor sequences become ER membrane spanning helices. It is also required for the post-translational insertion of tail-anchored/TA proteins in endoplasmic reticulum membranes. By mediating the proper cotranslational insertion of N-terminal transmembrane domains in an N-exo topology, with translocated N-terminus in the lumen of the ER, controls the topology of multi-pass membrane proteins like the G protein-coupled receptors. By regulating the insertion of various proteins in membranes, it is indirectly involved in many cellular processes (Probable).
Synonyms: C14orf122; FAM158A; CGI-112
Tractability: Antibody: UniProt places it where antibodies can reach, with high confidence. PROTAC: its protein half-life has been measured.
Gene: Protein-coding gene on chromosome 14 (24,138,958 to 24,142,023, reverse strand). Ensembl gene ENSG00000100908.
Subcellular location: Endoplasmic reticulum membrane
Gene Ontology:
Molecular function: membrane insertase activity; protein binding
Biological process: protein insertion into ER membrane by stop-transfer membrane-anchor sequence; tail-anchored membrane protein insertion into ER membrane
Cellular component: cytoplasm; EMC complex; endoplasmic reticulum membrane
Genetic constraint (gnomAD): Loss-of-function variants: 20 observed, 26.06 expected, observed/expected ratio (o/e) 0.77, 90% interval 0.54 to 1.12. The upper end of that interval is the gene's LOEUF score, 1.12, which puts it in group 4 of 6, group 1 being the genes least tolerant of losing a copy. Missense variants: 256 observed, 284.14 expected, observed/expected ratio (o/e) 0.9, 90% interval 0.81 to 1. Synonymous variants: 100 observed, 114.2 expected, observed/expected ratio (o/e) 0.88, 90% interval 0.74 to 1.03.
Homologues: Orthologues: chimpanzee EMC9 (99% identical), pig EMC9 (92% identical), dog EMC9 (92% identical), guinea pig EMC9 (91% identical), mouse Emc9 (90% identical), rat Emc9 (89% identical), rabbit EMC9 (73% identical), macaque EMC9 (65% identical), zebrafish emc9 (51% identical), tropical clawed frog emc9 (50% identical), Drosophila melanogaster EMC8-9 (33% identical), Caenorhabditis elegans F25H2.4 (25% identical). Paralogues in human: EMC8 (43% identical).